LVRN (laeverin)
Description:
Metalloprotease which may be important for placentation by regulating biological activity of key peptides at the embryo-maternal interface. On synthetic substrates it shows a marked preference for Leu-4-methylcoumaryl-7-amide (Leu-MCA) over Met-MCA, Arg-LCA and Lys-LCA. Cleaves the N-terminal amino acid of several peptides such as angiotensin-3, kisspeptin-10 and endokinin C.
Synonyms: APQ; AQPEP; FLJ90650; TAQPEP
Tractability: Small molecule: a drug acting on it is in phase 2 or 3 trials. Antibody: UniProt predicts a signal peptide or a membrane-spanning region. PROTAC: ubiquitination databases record sites on it.
Gene: Protein-coding gene on chromosome 5 (115,962,454 to 116,027,619, forward strand). Ensembl gene ENSG00000172901.
Subcellular location: Membrane
Gene Ontology:
Molecular function: metalloaminopeptidase activity; aminopeptidase activity; metallopeptidase activity; zinc ion binding
Biological process: peptide catabolic process; proteolysis
Cellular component: membrane
Genetic constraint (gnomAD): Loss-of-function variants: 81 observed, 88.45 expected, observed/expected ratio (o/e) 0.92, 90% interval 0.76 to 1.1. The upper end of that interval is the gene's LOEUF score, 1.1, which puts it in group 4 of 6, group 1 being the genes least tolerant of losing a copy. Missense variants: 1,273 observed, 1,112 expected, observed/expected ratio (o/e) 1.14, 90% interval 1.09 to 1.2. Synonymous variants: 442 observed, 423.18 expected, observed/expected ratio (o/e) 1.04, 90% interval 0.96 to 1.13.
Homologues: Orthologues: chimpanzee LVRN (99% identical), macaque LVRN (94% identical), pig LVRN (82% identical), dog LVRN (81% identical), guinea pig LVRN (79% identical), rabbit LVRN (73% identical), rat Lvrn (70% identical), mouse Lvrn (67% identical), tropical clawed frog lvrn (44% identical), zebrafish anpepla (34% identical), Drosophila melanogaster superdeath (29% identical), zebrafish anpeplb (29% identical), and 15 more. Paralogues in human: ANPEP (34% identical), ERAP1 (28% identical), ERAP2 (28% identical), ENPEP (27% identical), LNPEP (26% identical), NPEPPS (25% identical), TRHDE (23% identical), RNPEPL1 (13% identical), RNPEP (12% identical), LTA4H (12% identical), AOPEP (10% identical).
Diseases named in the same sentence as LVRN in open-access papers:
LVRN is named in the same sentence as 12 diseases in open-access papers, as found by Europe PMC text mining. Sharing a sentence is not in itself a finding about the gene and the disease. The quoted sentences say what the papers report.
preeclampsia (3 papers, 2016 to 2025). Preeclampsia is a hypertensive disorder of pregnancy that is characterized by new-onset hypertension with proteinuria presenting after 20 weeks of gestation, and depending on mild or severe forms may initially present with severe headache, visual disturbances, and hyperreflexia. "Conversely, some evidence suggests that lower serum laeverin levels at 22–24 weeks could indicate an increased risk of developing preeclampsia later." (PMID 39941247, 2025). "In cases of preeclampsia, maternal serum laeverin levels in the third trimester are lower compared to uncomplicated pregnancies, which is explained by the laeverin being entrapped in subcellular levels in the placenta." (PMID 39941247, 2025). "In cases of preeclampsia, there is often an overexpression of laeverin in the placenta, potentially leading to a significant difference in serum levels during the early third trimester." (PMID 39941247, 2025). "Galectin-13 (Gal-13) is predominantly produced by the syncytiotrophoblast, while laeverin is expressed on the outgrowing extravillous trophoblast, and both are thought to be biomarkers of preeclampsia." (PMID 38928055, 2024). "Half of the women who developed preeclampsia had plasma laeverin levels below the 5th percentile at 22–24 weeks gestation." (PMID 27887588, 2016). "It is known that preeclampsia leads to increased apoptosis of cytotrophoblasts or cell death, which might explain why laeverin accumulates in preeclamptic placentas." (PMID 27887588, 2016). "This leads us to speculate that laeverin might be trapped in the placenta during the development of preeclampsia." (PMID 27887588, 2016).
lung carcinoma (2 papers, 2013 to 2025). "Immunohistochemically, LVRN expression is detected in the lesions of vascular, lymphatic, and peritoneal invasion of ovarian, cervical, endometrial, breast, and lung cancers." (PMID 41024351, 2025). "Of the 12 common Significant DNA methylated genes common to Stages I and II, LY96 has been previously associated with lung cancer; ZNF577 and LVRN have been identified as methylated in lung cancer and renal carcinoma, but not in LUAD." (PMID 24369052, 2013).
Obesity (1 paper, 2019). Accumulation of substantial excess body fat. "Genes functionally non-reported in adipose tissue showed a link with a GWAS obesity trait (SLC19A3 and UPK3B genes) and a GWAS blood lipids trait (LVRN, CD300LG, and HAS1 genes)." (PMID 30816281, 2019).
cancer (1 paper, 2025). A tumor composed of atypical neoplastic, often pleomorphic cells that invade other tissues. "Fourth, the direct effects of anti‐LVRN antibody on cancer cells, including immunological modulation, and its inhibitory effects on hematogenous and lymphatic metastasis also need to be clarified using in vivo mouse models in the future." (PMID 41024351, 2025). "To examine the potential of anti‐LVRN mAb for clinical application, we conjugated monomethylauristatin E (MMAE, a potent anti‐cancer microtubule‐targeting agent) to control mAb (POG2, mouse anti‐porcine integrin α6, raised in our laboratory) and anti‐LVRN mAb (5‐23) via a valine‐citrulline linker." (PMID 41024351, 2025).
immune system diseases (1 paper, 2018). "DEGs that enriched to “immune system diseases” played critical roles in cell-matrix communication (THY1, LVRN, LUM, TIMP3, SPOCK1, LGALS3BP, FAT2, and SERPINE2) as well as inflammation (IL1R2, CD22, PTGES, TNFSF10, IL2RB, C3, SERPING1, and IL-17RE)." (PMID 30131724, 2018).
LVRN also shares sentences with these, for which no sentence is quoted: cervical cancer (1 paper); clear cell carcinoma (1); liver cancer (1); neurological disorders (1); Prader-Willi syndrome (1); prostate carcinoma (1); renal carcinoma (1).